CERS6 (ceramide synthase 6)
Diseases named in the same sentence as CERS6 in open-access papers (continued):
Sharing a sentence is not in itself a finding about the gene and the disease.
psoriasis (1 paper, 2022). An autoimmune condition characterized by red, well-delineated plaques with silvery scales that are usually on the extensor surfaces and scalp. "For example, the ceramide abundances in psoriasis lesional skin matched the increased expression of CERS3 and SPTLC2 and the decreased expression CERS6." (PMID 35900871, 2022). "Likewise, keratinocyte expression of CERS6 was decreased after incubation with TNF and IL-17A, which also mimicked the downregulation of CERS6 in psoriasis lesional skin." (PMID 35900871, 2022).
sarcopenia (1 paper, 2024). Progressive decline in muscle mass due to aging which results in decreased functional capacity of muscles. "Increased plasma SM (16:0) and CER (24:1) levels in men with sarcopenia reflected increased CER species with fatty acid acyl chain length preferences toward long (C16:0) and very‐long chains (C24:0 and C24:1), which CERS6 and CERS2, respectively, produce." (PMID 39229927, 2024).
skin cancer (1 paper, 2022). "Surprisingly, lower CERS6 gene expression was only observed in skin cancer." (PMID 36077841, 2022). "In contrast to CERS6, there was more SMPD1 mRNA, which encodes ceramide-generating acid sphingomyelinase, in skin cancer tissue than in nontumor tissue." (PMID 36077841, 2022).
ulcerative colitis (1 paper, 2025). An inflammatory bowel disease involving the mucosal surface of the large intestine and rectum. "The downregulation of FTO promotes the occurrence of ulcerative colitis (UC) by reducing the expression of CERS6 and exacerbates UC through m6A-dependent mechanisms." (PMID 40829428, 2025).
tumor (25 papers, 2013 to 2025). "For instance, CerS1 produces ceramides(18:0), which inhibit tumor growth, while CerS5 and CerS6 generate ceramides (16:0),which are associated with anti-apoptotic effects in headand neck squamous cell carcinoma.The CerS1-specific inhibitor P053 reduces ceramide (18:0)levels in HEK 293 cells." (PMID 39944803, 2024). "We also found that the tumor volume of KYSE150 xenografts significantly decreased after CERS6 was knocked out." (PMID 41203639, 2025). "We found that the CERS6 protein levels were significantly higher than in peri-tumor and normal tissues." (PMID 41203639, 2025). "CERS6 and SPTLC2 were classified into a high-risk group with higher hazard ratios (HR > 1) and higher expression in tumor tissues, but S1PR1 exhibited a protective effect (HR < 1) and lower expression in malignant tissues." (PMID 40057751, 2025). "The expression level of CerS6 was significantly upregulated in hepatocytes, cholangiocytes, and immune cells in both pre-tumor and HCC groups." (PMID 40057751, 2025). "Analysis of the key enzymes involved in ceramide synthesis and metabolism revealed a significant upregulation of Cers6 in hepatocytes, cholangiocytes, HSCs, and immune cells in both pre-tumor and HCC groups." (PMID 40057751, 2025). "The C16-ceramide synthesized by ceramide synthase 6 had anti-apoptotic roles in tumor cells when encountering endoplasmic reticulum (ER) stress." (PMID 37234408, 2023). "Other cancer types with statistical differences between Normal and Tumor groups revealed higher gene expression of CERS6." (PMID 36077841, 2022). "As a proof-of-concept, the sensitivity to cisplatin using an OSCC xenograft tumor formation assay has been reversed by the reduction of CerS6." (PMID 32121501, 2020). "For example, CerS1/C18 ceramides suppress HNSCC xenograft tumor growth, and CerS6/C16 ceramides induce HNSCC tumor proliferation in SCID mice." (PMID 31676768, 2019). "The anti-tumor effect of cladoloside C2 was significantly prevented in CerS6 shRNA-silenced xenograft models." (PMID 29416631, 2018). "In HNSCC cells, CERS1 overexpression or C18-ceramide treatment suppresses tumor growth, but CERS6 downregulation produces ER stress leading to apoptosis of cells." (PMID 29262618, 2017). "We observed that the anti-tumor effect of STD is partially prevented in CerS6 shRNA-silenced xenograft models." (PMID 26318294, 2015). "An integrative analysis of the gene expression in NCI-60 tumor cell lines revealed that the expression level of a ceramide synthase, namely ceramide synthase-6 (CerS6) decreases during EMT." (PMID 26682260, 2015). "STD treatment significantly inhibited tumor growth compared with control and led to the up-regulation of CerS6 and ceramide, as well as the activation of p38 kinase, in mouse HL-60 and K562 leukemic xenograft models." (PMID 26318294, 2015). "In humans, CERS6 ceramides inhibit apoptosis in tumor cells." (PMID 40822650, 2025). "Furthermore, the CERS6 protein levels in paired normal (N), peri-tumor (P), and cancerous (C) tissues of 21 ESCC patients were measured by Western blot." (PMID 41203639, 2025). "As for the present cohort, CERS6 expression level was correlated with pN status, whereas the level of miR‐101 expression was not, possibly because miR‐101 controls not only the expression of CERS6 but also that of other tumour‐related genes." (PMID 32902157, 2020). "Tumor status induced a significant increase in the expression of CerS2 (p < 0.0001), CerS6 (p < 0.0001), DEGS2 (p < 0.0001), SMPD1 (p < 0.05), and CLN3 (p < 0.0001); and a significant decrease in the expression of UGT8 (p < 0.0001) compared with expression in the corresponding non-tumor tissue." (PMID 26528430, 2015). "The anti-tumor effect of STD was partially prevented in CerS6 shRNA-silenced xenograft models." (PMID 26318294, 2015). "Additionally, Cers6 was upregulated in ECs and macrophages in the pre-tumor group." (PMID 40057751, 2025).
tumor (continued). "Altogether, the significant differences in the expression of CerS2, CerS6, DEGS2, SMPD1, and UGT8 sphingolipid genes in tumor tissue go hand in hand with elevation of ceramide levels." (PMID 26528430, 2015). "Ceramide species differentially regulate tumor growth and invasion, namely ceramide synthase-1 (CerS1, also known as longevity assurance gene 1, LASS1) and ceramide synthase-6 (CerS6 or LASS6)." (PMID 24970177, 2013). "The expression of ceramide synthase-6 genes has been shown to decrease in tumor cells in contrast to non-tumor cells." (PMID 38140081, 2023). "A previous study suggested that CerS6 overexpression might be involved in drug-induced Fas/CD95 activation and enhanced tumor cell killing." (PMID 26318294, 2015). "The mRNA levels of CERS6 were significantly lower in tumor tissue than in nontumor tissue." (PMID 36077841, 2022). "Data mining of our previous human HCC transcriptome dataset showed that the gene expression of CERS2, CERS4, CERS5, and CERS6 was significantly increased in HCC tumors compared with that in non-tumor adjacent tissues, while no obvious difference was observed in ASAH1 gene expression." (PMID 33803928, 2021).
cancer (21 papers, 2010 to 2025). A tumor composed of atypical neoplastic, often pleomorphic cells that invade other tissues. "Although mechanisms of motility between cancer cells and lymphocytes are different, it is possible that CerS6-deficient T cells have a reduced ability for homing and invasion of intestinal tissues." (PMID 29138469, 2017). "In cancer cells, altered membrane fluidity in CerS6-deficient cells reduces cell migration and invasion of in vitro." (PMID 29138469, 2017). "This proposed model is consistent with clinical evidence showing that both CERS6 and LASP1 are upregulated in different types of cancer, and that high expression is associated with poor prognosis." (PMID 37345118, 2023). "In an analysis of breast cancer, CERS6 overexpression conferred chemoresistance, while its inhibition significantly reduced growth, migration, and survival of cancer cells." (PMID 37345118, 2023). "CERS6 has been identified as a cancer-promoting factor for lung, colon, breast, and ovarian cancers as well as other malignant tumors." (PMID 37046655, 2023). "To further understand the pattern of CERS6 gene expression in cancers, we performed a pan-cancer analysis." (PMID 36077841, 2022). "We also showed that CERS6 stimulated lamellipodia formation, which is essential for cancer cell metastasis." (PMID 32902157, 2020). "Based on these results, we suggest that CERS6 is a protein that promotes cancer cell migration and metastasis." (PMID 32902157, 2020). "In order to analyse the functions of CERS6 in cancer, we treated LNM35 with small interfering or hairpin RNAs against CERS6 (siCERS6/shCERS6)." (PMID 32902157, 2020). "Based on these results, we suggest that CERS6 stimulates cancer cell migration through formation of a ceramide‐dependent lamellipodia structure." (PMID 32902157, 2020). "CERS6 was also found to be overexpressed in several other adult cancers when compared to normal tissue samples." (PMID 30206207, 2018). "Here, we observed that the levels of CERS6, responsible for the generation of C16-Cer, were as high in cancer cells and similar to the levels of CERS2 (8.7 ± 0.4) among all cell lines tested." (PMID 30206207, 2018). "As cancer cells continue to develop resistance to chemotherapeutic drugs and evolve new mechanisms to evade apoptosis, future studies on determining CERS6 as a biomarker for drug resistance in cancer are warranted." (PMID 30206207, 2018). "We have observed that after treatment of a panel of 10 cancer cell lines with 10 nM MTX (near IC50 for DHFR) the elevation of CerS6 protein took place in six cell lines." (PMID 26783755, 2016). "We previously reported that ceramide synthase 6 (CerS6) is elevated in response to folate stress in cancer cells, leading to enhanced production of C16-ceramide and apoptosis." (PMID 26783755, 2016). "CERS6, TCF7, and MYBL1 stood out as common regulators in at least four networks, all three TFs have been implicated in the cancer process." (PMID 26606983, 2015). "Interestingly, CERS6 mRNA was up-regulated in 13 other cancer types by analyzing the TCGA and GTEx databases." (PMID 41203639, 2025). "Recent research has shown that CERS6 plays a significant role in the development of cancer." (PMID 41203639, 2025). "CERS6 is employed for a similar pathological phenotype; thus, it is feasible that in addition to the physical interaction, these genes functionally coordinate and promote cancer metastasis." (PMID 37345118, 2023). "Other groups have also reported the cancer-promotion roles of CERS6." (PMID 37345118, 2023). "It is considered that the ternary complex of LASP1, CERS6, and actin may contribute to lamellipodia formation and cancer cell migration." (PMID 37345118, 2023).
cancer (continued). "Thus, we consider that cancer cells show a metastatic phenotype as a result of CERS6 and C16 ceramide to produce a PKCζ and RAC1 complex." (PMID 32902157, 2020). "Taken together, CERS6 may stimulate cancer cell migration by enzymatic activity to synthesize C16 ceramide." (PMID 32902157, 2020). "Expression of CerS6 shRNA also decreased the growth of SW480 cancer cells." (PMID 29138469, 2017). "We observed that CerS6 protein was markedly elevated in several cancer cell lines treated with MTX." (PMID 26783755, 2016). "Indeed, we have demonstrated that the MTX treatment of several cancer cell lines resulted in the elevation of CerS6 protein." (PMID 26783755, 2016). "Furthermore, while the elevation of CerS6 through a transient transfection induced strong antiproliferative effect in several cancer cell lines, the expression of CerS4 in our experiments had no noticeable effect on proliferation of A549 or HCT116 cells." (PMID 26783755, 2016). "Moreover, it appears that the prevention of CerS6 activation preserves cancer cells proliferation at conditions of folate stress." (PMID 26783755, 2016). "Therefore, targeting CERS6 might be a promising strategy for cancer therapy." (PMID 41203639, 2025). "Our work presents CerS6 and specifically CerS6 glycosylation, as a potential therapeutic target for the modulation of GSK3β and AKT signaling in cancer models." (PMID 39608570, 2024). "Our observation on higher levels of CERS6 and C16-Cer in T-ALL cell lines is consistent with a few other cancers as reported in the literature." (PMID 30206207, 2018). "It should also be noted that in some cell lines, CERS6 was found to inhibit cell migration, suggesting that the miR‐101‐ CERS6 pathway does not explain all of these findings; thus, diverse pathways likely contribute to have effects on cancer cell phenotypes." (PMID 32902157, 2020). "Together, these results suggest that CERS6 and/or C16 ceramide are required for the formation of a complex between LASP1 and β actin, and that CERS6 may form a ternary complex resulting in efficient lamellipodia formation and cancer cell migration." (PMID 37345118, 2023). "Interestingly, CerS6 itself, but not CerS4, induced strong antiproliferative effect in several cancer cell lines if elevated by transient transfection." (PMID 26783755, 2016).
metabolic disease (6 papers, 2015 to 2025). A congenital disorder (due to inherited enzyme abnormality) or acquired (due to failure of a metabolically important organ) disorder resulting from an abnormal metabolic process. "Recently, the roles of CerS6 and its derivative Cer (d18:1/16:0) in metabolic diseases has attracted widespread attention." (PMID 41154683, 2025). "Among the various ceramides with different acyl-chain length, CerS6-derived C16 ceramides contribute to metabolic disorders." (PMID 37513589, 2023).
mitochondrial disease (1 paper, 2015). "On the basis of its pivotal role in regulating cell death upon COX dysfunction, CerS6 might potentially represent a novel target for therapeutic intervention in mitochondrial diseases caused by COX dysfunction." (PMID 25766330, 2015).
CERS6 also shares sentences with these, for which no sentence is quoted: acute myeloid leukemia (2 papers); colon adenocarcinoma (2); diabetes (2); type 2 diabetes (2); adenocarcinoma (1); Alzheimer disease (1); brain cancer (1); breast tumors (1); Cachexia (1); cardiovascular disease (1); cutaneous melanoma (1); degenerative diseases (1); demyelinating disorders (1); esophageal squamous cell carcinoma (1); experimental autoimmune encephalomyelitis (1); graft-vs-host disease (1); head and neck cancer (1); insulinoma (1); kidney diseases (1); mantle cell lymphoma (1); metabolic syndrome (1); ovarian tumor (1); prostate carcinoma (1); T-cell acute lymphoblastic leukemia (1).